SET (SET nuclear proto-oncogene)
Diseases named in the same sentence as SET in open-access papers (continued):
Sharing a sentence is not in itself a finding about the gene and the disease.
lymph node metastasis (1 paper, 2015). "Clinicopathologic analysis showed that SET expression was significantly correlated with clinical stage (p < 0.001), and lymph node metastasis (p < 0.05)." (PMID 25945834, 2015). "Notably, we found that high SET expression was strongly correlated with the clinical stages and lymph node metastasis in NSCLC, which suggested that SET is closely associated with NSCLC progression." (PMID 25945834, 2015). "However, statistically significant correlations between high levels of SET expression were found with advanced TNM stage (P < 0.001), lymph node metastasis (P = 0.017)." (PMID 25945834, 2015).
lymphopenia (1 paper, 2024). Reduction in the number of lymphocytes. "Thymic egress is supported by our observation of T-cell lymphopenia and by the near-complete absence of KMT2D locus recombined cells in the peripheral T-cells of Kmt2d KO (LckMar-Cre+Kmt2d-SET-fl/fl) mice." (PMID 38765012, 2024).
malaria (1 paper, 2021). Malaria is a serious and sometimes fatal disease caused by a parasite that commonly infects a certain type of mosquito which feeds on humans. "To identify the H3K64 methyltransferases in the malaria parasite, we cloned, expressed, and purified 9 SET (Su (var) 3-9, Enhancer-of-zeste, and Trithorax) domains from P. falciparum as glutathione-S-transferase (GST)-tagged recombinant proteins." (PMID 33839154, 2021).
nematode infection (1 paper, 2016). "Many TF families such as TUB, TCP, SET, SBP, PHD, and Orphans have not been reported in the regulation of tomato leaf mold disease resistance, but some of these TFs have been reported in grapevine (Vitis amurensis) against downy mildew and in ramie against root-lesion nematode infection." (PMID 28105042, 2016).
osteosarcoma (1 paper, 2024). A usually aggressive malignant bone-forming mesenchymal neoplasm, predominantly affecting adolescents and young adults. "However, in osteosarcoma cell line HOS, SET knock-down (KD) suppresses the colony-formation ability without affecting c-Myc and E2F1." (PMID 38141761, 2024).
Schinzel-Giedion syndrome (1 paper, 2023). Schinzel-Giedion syndrome (SGS) is an ectodermal dysplasia syndrome chiefly characterized by a distinctive facial dysmorphism, hydronephrosis, severe developmental delay, typical skeletal malformations, and genital and cardiac anomalies. "Here, the authors show that the accumulation of the oncoprotein SET, as occurring in the rare Schinzel-Giedion syndrome, and associated histone hypo-acetylation interfere with normal enhancer repertoire employed during brain development." (PMID 37270547, 2023).
Sepsis (1 paper, 2023). Sepsis is defined as life-threatening organ dysfunction caused by a dysregulated host response to infection. "Expression analysis of four diagnostic biomarkers suggested that the sepsis samples in cluster A had higher expression of SET, LPIN1, and CD74; however, the expression of TXN was remarkably higher in cluster B." (PMID 37346041, 2023). "Through PCR analysis, it was found that levels of CD74, LPIN1, and SET were significantly decreased after sepsis in rats, whereas the level of TXN was significantly increased after sepsis in rats, which was consistent with the results of bioinformatics." (PMID 37346041, 2023). "Four ERRGs, namely SET, LPIN1, TXN, and CD74, have been identified as characteristic diagnostic biomarkers for sepsis." (PMID 37346041, 2023). "Another supportive fact for our study was that the mRNA expression levels of CD74, LPIN1, and SET were downregulated in rats with sepsis, whereas TXN was upregulated." (PMID 37346041, 2023). "In addition, a nomogram model was developed to explore the diagnostic effectiveness of the expression profiles of SET, LPIN1, TXN, and CD74 for sepsis in both cohorts." (PMID 37346041, 2023). "The association analysis illustrated notable relationships between four ERRGs (including SET, LPIN1, TXN, and CD74) and sepsis." (PMID 37346041, 2023). "Based on the expression profile of SET, LPIN1, TXN, and CD74, two molecular subgroups of sepsis were obtained with K = 2, with 375 samples in cluster A and 385 samples in cluster B." (PMID 37346041, 2023). "The expression profiles of SET, LPIN1, and CD74 were significantly lower in the sepsis patients, whereas the expression of TXN was much higher." (PMID 37346041, 2023).
tauopathies (1 paper, 2022). "SET is a protein with multiple functions ranging from regulation of gene expression, cell migration, survival and differentiation which has been implicated in the progression of solid and haematological malignancies as well as in tauopathies such as AD." (PMID 36345878, 2022).
testicular tumor (1 paper, 2025). "In addition to SPTBN4, 31 other molecules were analyzed, revealing potential testicular tumor markers such as TPI1, HMGN1, UGCG, NCL, SET, and EIF3K." (PMID 40321316, 2025).
triple-negative breast carcinoma (1 paper, 2021). An invasive breast carcinoma which is negative for expression of estrogen receptor (ER), progesterone receptor (PR), and human epidermal growth factor receptor 2 (HER2). "This is in agreement with the results of a previous report showing that targeting SET downregulates the CIP2A mRNA and increases PP2A activity in triple-negative breast cancer cells." (PMID 34244560, 2021).
cancer (83 papers, 2006 to 2025). A tumor composed of atypical neoplastic, often pleomorphic cells that invade other tissues. "In this paragraph, we review the mechanisms implicated in aberrant expression and activity of SET in cancer cells." (PMID 36345878, 2022). "It is interesting to note that COG112, a peptide antagonist of SET, inhibits SET association with Rac1, leading to decreased migration and invasion of cancer cells." (PMID 36345878, 2022). "SET directly interacts with PP2A-C to suppress its activity, and enhanced SET expression is associated with several cancers." (PMID 35069561, 2021). "Its exclusive association with cancers of the haematopoietic system has prompted a large number of investigations into the role of MLL/SET proteins in haematopoiesis, a summary of which was attempted in this review." (PMID 32389825, 2020). "A deregulation of SET expression has been clearly associated with the development of pathologies such as cancers and neurodegenerative diseases." (PMID 30052687, 2018). "Accumulating evidence has demonstrated upregulation of the oncoprotein SET in different types of cancer and its association with poor clinical outcomes." (PMID 29749127, 2018). "Since SET is a physiological endogenous inhibitor of PP2A, the amount of SET must be increased by overexpression of SET to cause cancer, and also to produce similar potency of inhibition by okadaic acid." (PMID 30341686, 2018). "SET was reported to act as an oncogene in tumorigenesis, and aberrant expression of SET was associated with cancer progression." (PMID 30072625, 2018). "Despite these findings, which underscore the clinical relevance of SET expression, little is known about the causes of its overexpression in cancer." (PMID 28903318, 2017). "To date, 30% of these proteins have been linked to disease states, of which 22 SET proteins have been associated with cancer or other diseases in humans or mouse models." (PMID 24738023, 2013). "Protein phosphatase 2A (PP2A) is an essential tumor suppressor, with its activity often hindered in cancer cells by endogenous PP2A inhibitory proteins like SE translocation (SET)." (PMID 38141761, 2024). "Accumulating evidence revealed that the degradations of c-Myc and E2F1 through PP2A inactivation are the dominant mechanisms of SET-mediated cancer cell stemness." (PMID 38141761, 2024). "More strikingly, SET overexpression is a frequent event among different types of cancer including lung carcinoma, suggesting that the aberrant expression of SET in adult cells contributes to tumor initiation and/or progression." (PMID 38355937, 2024). "SET is a multifunctional protein that acts as a cancer-promoting factor and inhibitor of protein phosphatase 2A (PP2A), a major serine/threonine protein phosphatase." (PMID 38674024, 2024). "SET/PP2A axis plays a pivotal role in the colony-formation ability of cancer cells and the stabilization of c-Myc and E2F1 proteins implicated in this process." (PMID 38141761, 2024). "On the contrary, our previous report showed that SET knockdown (KD) suppresses the colony-formation ability of all human cancer cell lines tested, but a decrease in c-Myc protein is observed in only some cell lines." (PMID 38141761, 2024). "Comparison of regulatory variants across populations revealed regulatory effects in GM only for genes implicated in cancer, including ST7, SET and ECT2." (PMID 37543566, 2023). "Recently, the effects of SET and CIP2A proteins on the mutations and drug resistance of cancer cells have provided new insights into cancer therapy." (PMID 37097392, 2023). "This review describes first the mechanisms of cancer progression by the okadaic acid class of compounds and second those by the SET and CIP2A proteins." (PMID 37097392, 2023).
cancer (continued). "Our findings establish SET as a key regulator of macrophage positioning and function within tumors and suggest that SET is a promising target for cancer immunotherapy." (PMID 36224346, 2022). "There are three major endogenous cellular inhibitors that regulate PP2A activity: Inhibitor 2 of PP2A (I2PP2A or SET), CIP2A and PME1, all of which have been heavily implicated in tumor promotion and are overexpressed in many cancer types." (PMID 35118387, 2022). "These cell lines showed a spectrum of genetic dependencies on KRAS, HRAS, BRAF, CALM1-3 (the three human CaM genes), the alpha isoform of the C subunit of the PP2A enzyme (PPP2CA) and an endogenous inhibitor of PP2A in cancer, SET." (PMID 35617282, 2022). "Multiple mechanisms including aberrant gene expression, splicing and cellular localization have been shown to contribute to aberrant activity of SET in cancer and in AD." (PMID 36345878, 2022). "Our results delineate the unique role of the PP2A inhibitor proteins in tumorigenesis, and potentially explain why SET and CIP2A are frequently overexpressed concomitantly with mutations in ERK-activating oncogenes in human cancers." (PMID 36463234, 2022). "SET is mainly located within the nucleus of the cells; however, in many forms of cancers and neurodegenerative diseases, SET translocates from its primarly nuclear localization to the cytoplasm, where it can form an inhibitory interaction with PP2A." (PMID 36345878, 2022). "Overall, these data provide strong evidence that SET plays a crucial role in cancer via a mechanism involving PP2A inhibition." (PMID 36345878, 2022). "In canine mammarian tumor cells lines of primary (CIP-p) and metastatic (CIP-m) origin, the role of SET overexpression was found specific for cancer progression at metastatic stage." (PMID 36345878, 2022). "The oncogenic role of SET has been characterized in several cancer models by targeted genetic deletion achieved by RNA interference." (PMID 36345878, 2022). "The multidirectional mechanism of the SET gene actions makes it one of the targets of anti-cancer therapy." (PMID 36012171, 2022). "SET nuclear proto-oncogene (SET) is positively correlated with the poor prognosis of patients with cancer and is known to promote EMT." (PMID 33435156, 2021). "Overexpression of SET perturbs various signalling pathways, and high SET levels correlate with drug resistance and a poor prognosis in various human cancers." (PMID 34244560, 2021). "Herein, we dissect the unique structural features of SMYD3 relative to other SET enzymes, with an emphasis on the implications for selective design of therapeutics for the clinical management of cancer." (PMID 35076487, 2021). "The suppression of SET expression leads to decreased cell proliferation in various types of cancer cells." (PMID 31557212, 2019). "Elevated SET protein levels are observed in various human tumors, and are positively correlated with the poor prognosis of patients with several types of cancer." (PMID 31557212, 2019). "In that study, we observed that SET protein level is increased not only in cancer cells, but also in some interstitial cells in tumor micro-environment." (PMID 31557212, 2019). "Endogenous inhibitors of PP2A such as SET have also been found to be upregulated in cancer cells, thereby leading to a reduction in PP2A activity." (PMID 31382469, 2019). "The main mechanism of PP2A inactivation in cancer is via the overexpression of the endogenous PP2A inhibitors SET (Suvar/Enhancer of zeste/Trithorax) and CIP2A (Cancerous Inhibitor of PP2A)." (PMID 31214504, 2019). "Such combinatorial benefit was further demonstrated in myeloid leukemia where the combination of a SET inhibitor (indirect PP2A activation) with a tyrosine kinase inhibitor resulted in synergistic anti-cancer effects." (PMID 31214504, 2019).
cancer (continued). "Using immunohistochemistry, SET protein was observed not only in cancer cells, but also in some interstitial cells." (PMID 31557212, 2019). "Next, we further explored the biological significance of mitotic phosphorylation of SET in cancer cell growth." (PMID 31097686, 2019). "Following these observations, activation of PP2A has been suggested as a potential cancer therapy, by inhibiting SET, or in combination therapy to prevent PP2A inhibition-mediated drug resistance." (PMID 31382469, 2019). "miR-502-3p is appreciated to target multiple protein-coding genes including SET that plays an important role in the development of various carcinomas." (PMID 31752906, 2019). "Accumulating evidence demonstrates that the expression and activity of SET correlate with cancer occurrence, metastasis, and prognosis." (PMID 29749127, 2018). "High levels of SET expression have been found to correlate with cancer occurrence, metastases, and prognosis." (PMID 29749127, 2018). "Since endogenous inhibitors of PP2A are physiological proteins found in various human cells, the overexpression of SET and CIP2A plays a vital part in causing cancer in humans." (PMID 30341686, 2018). "Many endogenous inhibitors of PP2A, like CIP2A and SET, are emerging as key players in cancer cell survival and drug resistance." (PMID 28402257, 2017). "Based on these observations, it seems likely that either the variable N-terminal region or putative modification(s) of the N-terminal region (in the case of SET isoform 2) decides the nuclear/extra-nuclear localization of SET in normal and cancer cells." (PMID 28978088, 2017). "PP2A can be inactivated in cancer cells due to increased accumulation of the endogenous SET and CIP2A oncoproteins, which bind to different subunits of PP2A to inhibit PP2A activity." (PMID 27705940, 2016). "We and others have shown that pharmacological re-activation of PP2A or silencing of SET inhibits the growth of cancer cells and reduces disease progression in vivo in murine models." (PMID 27705940, 2016). "PP2A is a tumor suppressor that can be inactivated in cancer cells due to increased accumulation of the SET and CIP2A oncoproteins." (PMID 27705940, 2016). "FTY720, a sphingosine analogue, was found to reactivate PP2A and promote apoptosis of cancer cells by disrupting SET-PP2Ac binding in some malignant diseases, including NSCLC." (PMID 26575017, 2016). "We observed that in normal prostate tissue SET expression was almost exclusively localized to the nucleus, however in clinical cancer samples was both increased in expression and localized to the cytosol." (PMID 26563471, 2015). "Of importance, SET plays an oncogenic role modulating signaling pathways with high relevance in human cancer." (PMID 25945834, 2015). "This analysis also lead us to the observation that in cancer specimens SET expression was both cytosolic and nuclear whereas it was almost exclusively nuclear in benign samples (right)." (PMID 26563471, 2015). "Several different molecular mechanisms to inhibit PP2A have been described in cancer cells including alterations in PP2A subunits or deregulation of endogenous PP2A inhibitors such as SET and CIP2A." (PMID 25726524, 2015). "The use of sphingolipids and, synthetic sphingolipid analogs, or newly developed SET inhibitors, as cancer therapeutics is likely to increase as we are better able to target SET to reactivate PP2A, leading to tumor suppression." (PMID 25642418, 2014). "Similar to CIP2A, SET plays a role in a variety of cancers and was originally discovered as a chimeric protein." (PMID 25642418, 2014). "The potential of the SET protein as a new target in cancer therapy has been explored using a peptide and sphingolipid (FTY720) to disrupt the SET-PP2A interaction." (PMID 24555657, 2014).